MFGE8 (milk fat globule EGF and factor V/VIII domain containing)
Description:
Plays an important role in the maintenance of intestinal epithelial homeostasis and the promotion of mucosal healing. Promotes VEGF-dependent neovascularization (By similarity). Contributes to phagocytic removal of apoptotic cells in many tissues. Specific ligand for the alpha-v/beta-3 and alpha-v/beta-5 receptors. Also binds to phosphatidylserine-enriched cell surfaces in a receptor-independent manner. Zona pellucida-binding protein which may play a role in gamete interaction. [Medin]: Main constituent of aortic medial amyloid.
Synonyms: MFG-E8; SED1; EDIL1; BA46; OAcGD3S; HsT19888; hP47; HMFG; MFGM; SPAG10
Tractability: Antibody: a drug acting on it is in phase 1 trials; UniProt places it where antibodies can reach, with high confidence; its Gene Ontology location is reachable by antibodies, with high confidence; UniProt predicts a signal peptide or a membrane-spanning region. PROTAC: ubiquitination databases record sites on it; its protein half-life has been measured.
Gene: Protein-coding gene on chromosome 15 (88,898,683 to 88,913,468, reverse strand). Ensembl gene ENSG00000140545.
Subcellular location: Membrane; Secreted; Cytoplasmic vesicle, secretory vesicle, acrosome membrane
Subcellular location (Human Protein Atlas): Cytosol; Predicted to be secreted
Pathways (Reactome):
Metabolism of proteins: Amyloid fiber formation; Post-translational protein phosphorylation; Regulation of Insulin-like Growth Factor (IGF) transport and uptake by Insulin-like Growth Factor Binding Proteins (IGFBPs)
Developmental Biology: Developmental Lineage of Mammary Gland Alveolar Cells
Gene Ontology:
Molecular function: phosphatidylserine binding; extracellular matrix structural constituent; integrin binding
Biological process: apoptotic cell clearance
Cellular component: extracellular exosome; extracellular matrix; extracellular region; extracellular vesicle; membrane; endoplasmic reticulum lumen; non-collagenous component of interstitial matrix; acrosomal membrane; external side of plasma membrane
Genetic constraint (gnomAD): Loss-of-function variants: 34 observed, 43.32 expected, observed/expected ratio (o/e) 0.78, 90% interval 0.6 to 1.04. The upper end of that interval is the gene's LOEUF score, 1.04, which puts it in group 4 of 6, group 1 being the genes least tolerant of losing a copy. Missense variants: 510 observed, 528.61 expected, observed/expected ratio (o/e) 0.96, 90% interval 0.9 to 1.04. Synonymous variants: 230 observed, 221.55 expected, observed/expected ratio (o/e) 1.04, 90% interval 0.93 to 1.16.
Homologues: Orthologues: chimpanzee MFGE8 (99% identical), macaque MFGE8 (96% identical), dog MFGE8 (67% identical), pig MFGE8 (66% identical), guinea pig MFGE8 (64% identical), rat Mfge8 (62% identical), mouse Mfge8 (61% identical), tropical clawed frog mfge8 (54% identical), zebrafish mfge8b (53% identical), zebrafish mfge8a (50% identical). Paralogues in human: EDIL3 (51% identical), CNTNAP5 (21% identical), CNTNAP4 (19% identical), CNTNAP1 (19% identical), CNTNAP2 (18% identical), F5 (18% identical), F8 (18% identical), CNTNAP3 (18% identical), CNTNAP3B (18% identical), CUBN (18% identical), NRP1 (17% identical), HEPH (16% identical), and 23 more.
Diseases named in the same sentence as MFGE8 in open-access papers:
MFGE8 is named in the same sentence as 137 diseases in open-access papers, as found by Europe PMC text mining. Sharing a sentence is not in itself a finding about the gene and the disease. The quoted sentences say what the papers report.
atherosclerosis (21 papers, 2012 to 2026). A disease characterized by the build-up of fatty material and calcium deposition in the arterial wall resulting in partial or complete occlusion of the arterial lumen. "Mice transplanted with MFGE8-deficient bone marrow have an increased necrotic core area at the atherosclerosis plaque lesion and an increased number of apoptotic cells, indicating defective efferocytosis." (PMID 41590849, 2025). "In atherosclerosis models, MFGE8 deficiency exacerbates inflammation by impairing phagocytic clearance and activating MAPK/NF-κB signaling." (PMID 40895313, 2025). "A meta-analysis revealed that the MFGE8 variants rs534125149 and rs201988637 independently protected against atherosclerosis." (PMID 38779685, 2024). "A recent Finnish study has uncovered a protective association against atherosclerosis with certain MfgE8 variants." (PMID 39131300, 2024). "Splice variants of MFGE8 have been associated with reduced risk of atherosclerosis in FinnGen, a large Finnish biobank study." (PMID 37523383, 2023). "A few other molecules have been implicated in the failure of efferocytosis in atherosclerosis, including Milk fat globule epidermal growth factor 8 (Mfge8) and Mer receptor tyrosine kinase (Mertk)." (PMID 36359349, 2022). "The increased expression of milk fat globule epidermal growth factor VIII (MFGE8) is associated with aging, atherosclerosis, hypertension, and diabetic arterial walls, and plays a crucial role in remodeling." (PMID 35203642, 2022). "Better characterization of MFGE8 effector functions would allow for identification of ways to increase tissue repair and could be important therapeutically in resolving tissue damage in diet-associated diseases, such as atherosclerosis and intestinal disease." (PMID 36538527, 2023). "We identified several genes, including Cemip, Lum, Mfge8, Spp1, and Serpina3, which are known to be involved in atherosclerosis-induced gene expression." (PMID 38289873, 2024). "Therefore, the inhibition of MFGE8 expression may reduce the risk of atherosclerosis." (PMID 38779685, 2024). "We identify MFGE8 as a potentially important gene involved in SMC plasticity in female atherosclerosis." (PMID 37589136, 2023). "The results of our study suggest that while ECM production (including the GRNMAGENTA KD genes, MFGE8) is maintained in female mice’s atherosclerosis progression, it appears downregulated in male mice." (PMID 37589136, 2023). "Reduction of expression of MFGE8 in diabetic mouse models alleviated atherosclerosis, a major complication of diabetes." (PMID 31811237, 2019). "Among these, expression of the KD gene Mfge8 (milk fat globule EGF and factor V/VIII domain containing) of GRNMAGENTA was significantly downregulated in late-stage atherosclerosis in male mice, while expression was maintained in female plaques." (PMID 37589136, 2023). "Finally, the mice ortholog of key driver gene MFGE8 (milk fat globule EGF and factor V/VIII domain containing) showed retained expression in advanced plaques from female mice but was downregulated in male mice during atherosclerosis progression." (PMID 37589136, 2023).
breast carcinoma (18 papers, 2012 to 2025). "RBM7 knockdown enhanced aggressiveness of breast cancer relying on MFGE8 splicing switch to the short variant and NF-κB pathway activation." (PMID 38995840, 2024). "Only KTR14, KRT16, CXCL9, and CFD in BRCA1 Ovarian Cancer and TSPAN7 and CDKN2C in BRCA2 ovarian cancers were highly upregulated, and KANK4, MFGE8, LINC00346, and SA100A1 in BRCA1 mutated breast cancer, and MAGEA4 in BRCA2 breast cancers." (PMID 40647506, 2025). "Next, we sought to assess if MFGE8 splicing switch is responsible for acquisition of aggressive feature in RBM7-silenced breast cancer cells." (PMID 38995840, 2024). "Above all, our findings uncovered a previously unidentified role of RBM7 in breast cancer metastasis via coupling MFGE8 splicing switch and NF-κB signaling activation, suggesting a new therapeutic target and prognostic predictor for breast cancer." (PMID 38995840, 2024). "Overall, our findngs implicated that activated NF-κB pathway worked in concert with MFGE8 splicing transition to spur metastasis in RBM7-depleted breast cancer." (PMID 38995840, 2024). "To corroborate the role of MFGE8 splicing shift in RBM7- regulated breast cancer cell invasion, we transfected triple-negative breast cancer cells with ASOs directed against RBM7-binding motif and examined the potential impact on cell aggressiveness." (PMID 38995840, 2024). "(F) The mechanistic model of how RBM7 regulated metastasis of breast cancer through regulating MFGE8 splicing switch." (PMID 38995840, 2024). "The secreted MFGE8 is the ligand for αVβ3-5 integrins and has been shown to influence the viability, invasion and migration of breast cancer cells." (PMID 35158871, 2022). "Several of the LXRE genes predicted increased regression-free survival in breast cancer subjects, among which Ptgs2, Mfge8, Anxa1, Spp1, S100a9 and Cd14 are biomarkers for MDSC and Treg cells." (PMID 33780491, 2021). "Here, we show by immunohistochemistry on a collection of human ovarian cancers that MFGE8 is overexpressed in 45% of these tumors, and we confirm that it is specifically overexpressed in the triple-negative subtype of human breast cancers." (PMID 23977342, 2013). "A protumoral function of MFGE8 has consequently been documented for a few types of human cancers, including melanoma, a subtype of breast cancers, and bladder carcinoma." (PMID 23977342, 2013). "Indeed, major gene candidates were identified including IL6, VEGFA and MFGE8 that may play important role in the regulation of TME in breast cancer." (PMID 37975220, 2024). "In some types of human cancers, a pro-tumoral role of MFGE8 has been demonstrated, based on high overexpression during tumor progression, and/or on analysis of mouse models: these cancers include bladder carcinoma (our own work), melanoma, and the triple-negative subtype of breast cancer." (PMID 23977342, 2013). "In BRCA1-mut breast cancer, KANK4, MFGE8, LINC00346, and A100A1 were upregulated (more than 3-fold change), and in BRCA2-mut breast cancers, MAGEA4 was highly expressed (more than 4-fold change)." (PMID 40647506, 2025). "Taken together, these data above indicated that both MFGE8 splice switch and NF-κB pathway activation are required for mediating the pro-metastasis activity of RBM7 reduction in breast cancer." (PMID 38995840, 2024). "AP-MS and BioID experiments were performed for MFGE8 to explore its protein–protein interaction network to better understand the high expression of MFGE8 in TNBC and its correlation with poor prognosis in breast cancer." (PMID 32591639, 2020). "Meanwhile, the migrative and invasive ability of breast cancer cells treated with ASOs was significantly boosted, further suggesting that RBM7-knockdown stimulated aggressiveness of breast cancer at least partially relies on the control of MFGE8 AS." (PMID 38995840, 2024).
breast carcinoma (continued). "The observed cooperative effects of blocking MFGE8 and KLK5/7 with COX-2 inhibition in reducing tumor growth provides an important rationale for developing COX-2 inhibitor-based combination therapies for breast cancer patients." (PMID 33588911, 2021). "However, in some other cancers, such as Hormone Receptor (HR) and/or HER2-expressing human breast cancers, MFGE8 is not overexpressed, and it seems instead to prevent tumor progression." (PMID 23977342, 2013).
Sepsis (12 papers, 2011 to 2024). Sepsis is defined as life-threatening organ dysfunction caused by a dysregulated host response to infection. "The decrease of MFGE8 contributes to the accumulation of apoptotic cells, leading to a surge in pro-inflammatory cytokines, which is responsible for the progression and deterioration of sepsis." (PMID 33995102, 2021). "It has been demonstrated that DC-derived exosomes contain MFGE8, CD63, Toll-like receptors, adhesion molecules, co-stimulatory molecules, MHC-peptide complexes, and miRNA, which regulate the immune function of DCs, macrophages and lymphocytes during sepsis." (PMID 33995102, 2021).
melanoma (11 papers, 2013 to 2024). A malignant, usually aggressive tumor composed of atypical, neoplastic melanocytes. "In this study, we showed that MDSCs induce the migration of B16F10 mouse melanoma cells by secreting MFGE8, and MFGE8 neutralization suppressed their migration." (PMID 34440100, 2021). "TGF-β treatment of MDSCs resulted in increased MFGE8 secretion and addition of MFGE8 neutralizing antibody demonstrated that MDSC-derived MFGE8 promoted the migration of B16F10 melanoma cells." (PMID 34440100, 2021). "B16F10 melanoma secreted MFGE8 (1.65 ± 0.04 ng/mL), which is similar amount of MFGE8 secreted by Mo-MDSCs and Gr-MDSCs without TGF-β (1.06 ± 0.44 ng/mL and 1.91 ± 1.23 ng/mL, respectively) where S-MFGE8 is preferentially expressed over L-MFGE8." (PMID 34440100, 2021). "MFGE8 has also been reported to protect melanoma cell lines from stressful conditions induced by chemotherapy leading to apoptosis." (PMID 23977342, 2013). "Taken together, these data show that MFGE8 induces metastasis of B16F10 melanoma." (PMID 34440100, 2021). "Furthermore, we hypothesized that MFGE8 could be an important effector molecule used by MDSCs to promote the metastasis of B16F10 melanoma." (PMID 34440100, 2021). "MFGE8 acts at two levels, by increasing vascular endothelial growth factor (VEGF) and ET-1 expression in mesenchymal stromal cells and by enhancing M2 polarization of macrophages, to increase melanoma tumor angiogenesis." (PMID 36059952, 2022). "In addition, co-culturing MDSCs with B16F10 melanoma cells increased B16F10 cell migration, while MFGE8 neutralization decreased their migration." (PMID 34440100, 2021). "MFGE8 was not expressed by the melanoma cells, rather it was expressed variably by the hepatocytes, with those directly adjacent to the mUM showing strong expression of this protein." (PMID 33008022, 2020). "MFGE8 did not directly increase MDSC effector molecule expression, but MDSC-derived MFGE8 promoted the metastasis of B16F10 melanoma cells, suggesting that MDSC-derived MFGE8 could be a promising target for metastatic cancer therapies." (PMID 34440100, 2021).
Autoimmunity (10 papers, 2012 to 2024). The occurrence of an immune reaction against the organism's own cells or tissues. "At the same time, the genetic depletion of MFG-E8 leads to murine autoimmunity linked to the impaired clearance of germinal center B cells due to the role of MFGE8 in binding to PS on apoptotic B cells to facilitate their engulfment by macrophages." (PMID 33924911, 2021). "Additionally, MFGE8 gene polymorphisms have been associated with autoimmunity development in humans." (PMID 35268273, 2022). "Our aim was to explore whether four MFGE8 variants and MFGE8 serum levels are associated with autoimmunity susceptibility and autoimmune related atherosclerosis." (PMID 35268273, 2022). "Mice lacking LT or LT receptors, which are devoid of FDCs, or lacking the bridging protein Mfge8 itself, are significantly susceptible to autoimmunity suggesting the role of FDCs in protection against autoimmunity by expediting the removal of potentially self-reactive debris from the GCs." (PMID 23049531, 2012). "MFGE8 (also known as lactadherin) is a soluble glycoprotein which plays a negative role in regulating inflammation and autoimmunity by facilitating apoptotic cell clearance." (PMID 32945126, 2020).
systemic lupus erythematosus (10 papers, 2012 to 2023). An autoimmune multi-organ disease typically associated with vasculopathy and autoantibody production. "Milk Fat Globule Epidermal Growth Factor 8 (MFGE8) deficiency and gene polymorphisms have been previously linked to systemic lupus erythematosus (SLE)-like and SLE development." (PMID 35268273, 2022). "Two common SNP were previously identified in the open reading frame of the MFGE8 gene called MFGE8 R3S (rs4945 for nucleotide C>A) and MFGE8 M76L (rs1878326 for nucleotide 226 A>C), associated with an increased risk of systemic lupus erythematosus." (PMID 22438901, 2012). "In humans, the association of two nucleotide polymorphisms in the coding region of MFGE8 predisposes subjects to systemic lupus erythematosus, suggesting that these single nucleotide polymorphisms (SNP) lead to a dysfunctional MFGE8." (PMID 22438901, 2012). "Of interest, MFGE8 deficiency in mice delays the clearance of apoptotic lymphocytes, leading to enhanced self-antigen presentation and generation of a disease reminiscent of human systemic lupus erythematosus (SLE)." (PMID 35268273, 2022).
autoimmune disease (9 papers, 2013 to 2024). A disorder resulting from loss of function or tissue destruction of an organ or multiple organs, arising from humoral or cellular immune responses of the individual to their own tissue constituents. "In mouse models, MFGE8 failure has been linked to the incidence of autoimmune diseases." (PMID 38734017, 2024). "Therefore, the expression level of MFGE8 is a very important factor in its function, and can be said to be related to the pathogenesis of autoimmune diseases including SLE." (PMID 31811237, 2019). "Unravelling the mechanisms of MFGE8 overexpression-driven SLE may increase knowledge about autoimmune disease, but additional studies are required." (PMID 31811237, 2019).
colitis (6 papers, 2014 to 2025). Inflammation of the colon. "MFGE8 production is reportedly downregulated during the initiation of colitis, whereas it increases from the healing phase to restore homeostasis mechanisms." (PMID 36982414, 2023). "Loss of MFGE8 results in delayed recovery after DSS treatment, but treatment with recombinant MFGE8 attenuates damage in colitis models." (PMID 36538527, 2023). "Administration of recombinant MFGE8 preserved colon integrity in DSS-induced colitis mice." (PMID 37770932, 2023). "MFGE8 is also proven to be beneficial to colitis and other intestinal damages." (PMID 35674581, 2022). "MFGE8, a glycoprotein secreted by various cells, is involved in the phagocytic clearance of apoptotic cells, effectively attenuating inflammation, promoting intestinal mucosal healing, and maintaining mucosal integrity in DSS and TNBS-induced mouse colitis." (PMID 36982414, 2023).